S1PR3 (sphingosine-1-phosphate receptor 3)
Diseases named in the same sentence as S1PR3 in open-access papers (continued):
Sharing a sentence is not in itself a finding about the gene and the disease.
lung adenocarcinoma (6 papers, 2019 to 2025). A carcinoma that arises from the lung and is characterized by the presence of malignant glandular epithelial cells. "S1PR3 was found to be more abundant in human lung adenocarcinoma tissue compared to normal tissue and was linked to S1P-mediated proliferation of adenocarcinoma cells." (PMID 39940821, 2025). "In lung adenocarcinoma cells, S1P/S1PR3 was also found to enhance EGFR expression, promote proliferation, and anchor nondependent growth, thereby promoting tumor progression." (PMID 35799611, 2022). "In lung adenocarcinoma cells, S1PR3 is increased and elicits EGFR expression." (PMID 39940821, 2025). "In addition, the ectopic expression of S1PR3 promoted the growth and metastasis of human lung adenocarcinoma cells in mice." (PMID 35799611, 2022). "Earlier studies showed that S1P/S1PR3 signaling increases the expression of endothelial growth factor receptors (EGFR) in lung adenocarcinoma cells through the Rho kinase pathway and enhances EGF-stimulated cell proliferation, cell invasion, and colony formation." (PMID 31807117, 2019).
lung fibrosis (6 papers, 2014 to 2025). "Among S1PRs, S1PR3 mediates the development of PF, and S1pr3-deficient mice exhibit attenuated inflammation and lung fibrosis after bleomycin (BLM) challenge through decreased connective tissue growth factor." (PMID 40092491, 2025). "Agonism of S1PR3, on the other hand, has been implicated in the development of radiation- and bleomycin-induced pulmonary fibrosis in mice." (PMID 35860272, 2022). "Here, we found increased expression of S1pr3 in the lung during the process of bleomycin-induced pulmonary fibrosis in mice and specific overexpression of S1pr3 in the infiltrated M2 macrophages." (PMID 40092491, 2025). "A previous study illustrated the binding relationship between miR-495-3p and S1PR3 in pulmonary fibrosis." (PMID 35200103, 2022). "It has been shown that miR-495-3p plays a protective role in pulmonary fibrosis by downregulating S1PR3 expression." (PMID 35200103, 2022). "S1PR2-aAb and S1PR3-aAb showed a particular association with both PAH and lung fibrosis, in line with their established local biochemical function." (PMID 35860272, 2022). "In mouse models of lung fibrosis, S1PR1 was shown to inhibit lung fibrosis whereas S1PR3 mediated the development of lung fibrosis." (PMID 29782549, 2018). "More recently, S1pr3 deletion was reported to attenuate bleomycin–induced lung fibrosis." (PMID 29782549, 2018). "Taken together, our research showed that inhibition of S1pr3 ameliorates bleomycin-induced pulmonary fibrosis by reducing macrophage M2 polarization via the PI3K/Akt-Stat3 signaling pathway, indicating that S1pr3 may be a potential target for pulmonary fibrosis treatment." (PMID 40092491, 2025). "Moreover, miR-495-3p was reported to target S1PR3 to mitigate pulmonary fibrosis." (PMID 35200103, 2022). "However, the S1PR3–expressing cell type that plays a crucial role in lung fibrosis, and the critical intracellular signaling pathway downstream of S1PR3 are unknown." (PMID 29782549, 2018). "Moreover, the S1pr3 inhibitors CAY10444 and TY52156 exerted protective effects on pulmonary fibrosis in mice." (PMID 40092491, 2025). "Here, we describe for the first time the prevalence of S1PR-aAb including the first identification of S1PR2- and S1PR3-aAb in a large cohort of patients and healthy individuals, and report their potential use as both biomarkers and potential therapeutic targets in SSc, PAH, and/or lung fibrosis." (PMID 35860272, 2022). "The increased prevalence of S1PR2- and S1PR3- but not S1PR1-specific aAb in SSc-PAH patients may thus point towards an autoimmune-supported pathomechanism that could contribute to elevated pulmonary vascular resistance and the development of lung fibrosis in SSc-associated PAH." (PMID 35860272, 2022).
Osteopenia (6 papers, 2014 to 2024). Osteopenia is a term to define bone density that is not normal but also not as low as osteoporosis. "S1pr3‐null mice are viable, fertile and superficially normal, however, 8‐month‐old S1pr3‐deficient mice showed osteopenia and reduced bone formation." (PMID 34585505, 2022). "In contrast, 8-month-old S1pr3-deficient mice displayed osteopenia and reduced boneformation, while bone resorption parameters were unaffected." (PMID 25333900, 2014). "Moreover, since S1pr2-deficient mice, similar to S1pr3-deficient mice were found to display osteopenia, it might be informative to combine the S1P2-deficiency with mouse models of increased S1P levels (including Sgpl1-deficient mice) in future experiments." (PMID 31314788, 2019). "In contrast, the role of S1PR3 has remained rather ambiguous, as deletion led to osteopenia in aged receptor knockout animals, whereas activation induced bone matrix secretion and triggered mineralization." (PMID 38477738, 2024). "Conversely, S1PR3 global knockout mice are viable and exhibit no developmental defects at 3 months; however, osteopenia is seen at 8 months." (PMID 37108099, 2023).
diabetes (5 papers, 2012 to 2024). "Studies have shown that diabetes/hyperglycemia specifically triggered S1P/S1PR3 signaling and exacerbated HIRI by facilitating M1 polarization and inhibiting M2 polarization." (PMID 39256347, 2024). "Conversely, induction of S1PR2 has been related to diabetes whereas expression of S1PR3 was unchanged." (PMID 32033121, 2020). "Regarding S1PR3, single-cell RNA profiling indicates its expression in mesangial cells and may contribute to cell proliferation but its exact role in diabetes-induced kidney complications requires further evaluation." (PMID 39384640, 2024). "The results of this research may help explain the induction of tacrolimus-induced posttransplantation diabetes mellitus via the low expression of muscle genes including Tpm3, Tnnc1, Tnnt1, Tnni3, Hrh3, Apln, S1pr3, and Cxcl12." (PMID 31998808, 2020). "Recent G-protein-coupled receptor profiling revealed that S1PR3 is one of the most upregulated GPCRs in activated kidney fibroblasts in models of UUO, diabetes, adriamycin nephropathy, and folic acid nephropathy." (PMID 39384640, 2024).
glioblastoma (5 papers, 2019 to 2024). The most malignant astrocytic tumor (WHO grade IV). "Nonetheless, in the U-118 MG and U-373 MG human glioblastoma cell lines, both S1PR1 and S1PR3 concurrent expression promote the motility and invasiveness of glioblastoma cells through overlapping but distinct mechanisms in vitro." (PMID 38894892, 2024). "In turn, in an autocrine/paracrine manner, the extracellular S1P stimulates glioblastoma cell growth and GEC migration and tubule formation in a S1PR1/S1PR3-dependent trend." (PMID 35326565, 2022). "The expression of S1PR2 by glioblastoma cells may be explained by their requirement to balance the input from other expressed S1P receptor subtypes, such as S1PR1 or S1PR3." (PMID 31062076, 2019).
injury (5 papers, 2015 to 2025). Damage inflicted on the body as the direct or indirect result of an external force, with or without disruption of structural continuity. "To investigate the potential role of S1PR2 and S1PR3 in BMM migration during cholestatic liver injury, we performed an EGPF-positive BM cell transplantation experiment followed by BDL-induced liver injury with the administration of JTE-013 or CAY-10444." (PMID 26324256, 2015). "Notably, we observed that SPHK1, S1PR3, and S1PR5 in the sphingolipid metabolism pathway could be potential therapeutic targets for the prevention of acute liver injury induced by APAP, as mediated by the Ks extract." (PMID 40811614, 2025).
Insulin resistance (5 papers, 2021 to 2023). Increased resistance towards insulin, that is, diminished effectiveness of insulin in reducing blood glucose levels. "Therefore, it is likely that the increase in insulin resistance and glucose intolerance observed in S1PR3−/− mice maybe due to a combined dual effect of the loss of S1PR3 signalling and increased expression of S1PR2." (PMID 35094654, 2022). "On a HFD, weight gain was similar in both S1PR3-/- mice and WT littermates; however, HFD-fed S1PR3-/- mice exhibited a phenotype of partial lipodystrophy, exacerbated insulin resistance and glucose intolerance." (PMID 35094654, 2022). "In contrast, ApoM was shown to promote insulin secretion and antagonize insulin resistance after activating S1PR1 and/or S1PR3 signaling." (PMID 37867511, 2023). "Among the eight potential key metabolites, sphinganine 1-phosphate is able to protect against the development of hepatic insulin resistance by activating the Akt pathway via the receptor subtypes S1PR1 and/or S1PR3 and by enhancing mitochondrial functions." (PMID 38201125, 2023). "Insulin resistance and glucose intolerance was exacerbated in HFD-fed S1PR3−/− mice, suggesting a protective role for S1P-S1PR3 signalling axis in regulation of metabolic homeostasis." (PMID 35094654, 2022).
Obesity (5 papers, 2022 to 2024). Accumulation of substantial excess body fat. "Our data, however, show a clear function for S1PR3 in hepatic steatosis and inflammation associated with diet-induced obesity." (PMID 35094654, 2022). "All the data indicated that the S1P/S1PR1/S1PR3-YAP signaling could be an underlying mechanism contributing to aggressive behavior of tumor growth in obesity-lymphoma." (PMID 36600310, 2023). "• S1P-S1PR1/S1PR3-YAP signaling mediated lymphomagenesis contributing to tumor aggressive growth in obesity-lymphoma." (PMID 36600310, 2023). "This study therefore demonstrates that S1P is protective in the setting of obesity and T2D, and, that its protective effects are partly due to signalling via the S1PR3 in AT and liver." (PMID 35094654, 2022). "To directly assess the contribution of S1PR3 to obesity and its metabolic consequences, we compared the physiological and biochemical consequences of a 16-wk HFD on WT and S1PR3−/− mice." (PMID 35094654, 2022). "Accordingly, S1PR3, IQCG, and TF are common in HCL, aging, and CVD; ACSL1, THBD, and HNF4A are repeated in HTN, obesity, and CVD." (PMID 36035865, 2022). "S1P/S1PR initiated the feedback loops, whereby S1P-S1PR1/S1PR3-YAP signaling mediated lymphomagenesis contributing to tumor aggressive growth, while S1P-ALOX15 signaling mediated TAMs contributing to immunosuppressive microenvironment in obesity-lymphoma." (PMID 36600310, 2023). "In conclusion, S1P/S1PR initiated the feedback loops, whereby S1P-S1PR1/S1PR3-YAP signaling mediated lymphomagenesis contributed to tumor aggressive growth, and S1P-ALOX15 signaling mediated TAMs contributed to immunosuppressive microenvironment in obesity-lymphoma." (PMID 36600310, 2023).
psoriasis (5 papers, 2021 to 2025). An autoimmune condition characterized by red, well-delineated plaques with silvery scales that are usually on the extensor surfaces and scalp. "Taken together, these findings highlight the differential expression patterns of S1P receptors in psoriasis and underscore the specific association of the expression of S1PR3, which is predominantly expressed in keratinocytes, with the severity of psoriasis." (PMID 39833165, 2025). "S1PR3 was predicted to be the target gene of miR-766-3p, which is associated with the psoriasis-related Ras/pERK and PI3K/AKT pathways and acts as a pro-inflammatory cytokine." (PMID 34992498, 2021). "S1PR3-KO mice displayed a marked attenuation of the phenotypic features of psoriasis, as evidenced by macroscopic examination." (PMID 39833165, 2025). "SGPL1 expression decreased with the severity of psoriasis, whereas S1PR3 expression increased, showing that S1PR3 was negatively related to SGPL1 expression and was positively related to psoriasis severity in IMQ-induced mice." (PMID 39833165, 2025). "Genetic deletion of S1pr3 in mice or pharmacological inhibition of S1PR3 significantly attenuates psoriasis-like skin inflammation, decreasing epidermal hyperplasia, dermal angiogenesis, and inflammatory mediator production." (PMID 39833165, 2025). "Our findings demonstrated that the protective role of FTY720 in psoriasis was mediated by internalized S1PR3, highlighting the significance of S1PR3 in the pathogenesis of psoriasis." (PMID 39833165, 2025). "In summary, these findings demonstrate that keratinocyte S1PR3 is closely related to the development of psoriasis." (PMID 39833165, 2025). "S1PR3 knockout alleviated the manifestations and pathological features of psoriasis by inhibiting the hyperproliferation and inflammatory response." (PMID 39833165, 2025). "Crucially, S1PR3 inhibition reduced both Src and STAT3 activation in vivo, corroborating our in vitro findings and supporting the S1PR3–Src–STAT3 signaling axis as a key driver of psoriasis pathogenesis." (PMID 39833165, 2025). "To further investigate the role of keratinocyte-specific S1PR3 in psoriasis progression, we generated keratinocyte-specific S1PR3knockdown mice through intradermal injection of adeno-associated virus serotype 9-shS1PR3 with the K14 promoter (K14-AAV9-shS1PR3)." (PMID 39833165, 2025). "Through both genetic and pharmacological approaches, we explored the therapeutic potential of targeting S1PR3 in psoriasis." (PMID 39833165, 2025). "Conversely, S1PR3 expression was downregulated after anti-psoriasis treatment, indicating the important role of S1PR3 expression in the progression of psoriasis." (PMID 39833165, 2025). "To elucidate the role of S1PR3 in psoriasis pathogenesis, we subjected S1PR3-KO mice to IMQ for 7 days." (PMID 39833165, 2025). "To evaluate the therapeutic potential of S1PR3 inhibition in psoriasis, we administered the S1PR3 antagonist TY (3 mg/kg/day) to mice with IMQ-induced psoriasiform dermatitis for six consecutive days." (PMID 39833165, 2025). "Since the levels of sphingosine-1-phosphate derived from ceramide and sphingolipid metabolism are increased in psoriasis, we identified increased S1PR3 as a key receptor closely related to the severity of psoriatic lesions in this study." (PMID 39833165, 2025). "This is believed to be because S1PR3 affects cell proliferation and inflammation in psoriasis via the AKT/mTOR pathway." (PMID 37830566, 2023). "We found 28 potential target genes and selected S1PR3, which is associated with the Ras/pERK and PI3K/AKT pathways reported in psoriasis and plays role in pro-inflammatory cytokine regulation." (PMID 34992498, 2021). "In conclusion, we have established that downregulation of lncRNA H19 promoted the proliferation of keratinocytes and skin inflammation by up-regulating miR-766-3p expression levels and inhibiting activation of S1PR3 through the AKT/mTOR pathway in psoriasis." (PMID 34992498, 2021).
psoriasis (continued). "We established that downregulation of lncRNA H19 promoted the proliferation of keratinocytes and skin inflammation by up-regulating miR-766-3p expression levels and inhibiting activation of S1PR3 through the AKT/mTOR pathway in psoriasis." (PMID 34992498, 2021). "Furthermore, S1PR3-KO markedly improved psoriasis-related phenotypes, including erythema, scaling, and infiltration, resulting in a reduced PASI scores." (PMID 39833165, 2025). "Targeting the S1P/S1PR3/STAT3 axis might serve as a potential therapeutic strategy for patients with psoriasis." (PMID 39833165, 2025). "In addition, the persistent activation of STAT3 in psoriasis was attributed to elevated S1PR3 in the epidermal skin, resulting in positive feedback between S1PR3 and STAT3." (PMID 39833165, 2025). "In this study, we found that S1PR3 expression was closely related to the severity of psoriasis." (PMID 39833165, 2025). "Our analysis revealed 370 psoriasis-upregulated genes that were suppressed by TY, including the key hyperproliferation markers K16 and K17, suggesting a direct anti-hyperproliferative effect on keratinocytes after S1PR3 inhibition." (PMID 39833165, 2025). "We found that expression of S1PR3 was downregulated in psoriasis tissue." (PMID 34992498, 2021). "We confirmed that S1PR3 was downregulated in psoriasis tissues and M5-induced HaCaT cells." (PMID 34992498, 2021). "Furthermore, the relationship between S1PR3 and psoriasis has also been studied to some extent, and RT-qPCR and immunohistochemistry have shown that the S1PR3 gene and protein expression are downregulated in human psoriasis skin." (PMID 37830566, 2023). "The increased expression of S1PR3 was the major cause of persistent STAT3 activation in psoriasis keratinocytes, suggesting that S1PR3 and STAT3 are involved in interactions between sphingolipid metabolites and abnormal proliferation in psoriasis patients." (PMID 39833165, 2025). "Other psoriasis-specific enriched pathways included lipid metabolism (e.g. ACOT4, S1PR3), keratinization (e.g. LCE5A, KRT5/7/16), neutrophil degranulation, and antimicrobial peptides (e.g. LTF, DEFB4A, S100A7-9)." (PMID 38433843, 2024). "S1PR3 KO in vitro and in vivo inhibited keratinocyte proliferation and STAT3 phosphorylation, confirming the role of S1PR3 in STAT3 activation and the pathogenesis of psoriasis." (PMID 39833165, 2025). "Our results indicated that sodium orthovanadate treatment did not influence the P-STAT3 levels in HaCaT cells, compared to IL-6 and CYM treatment, suggesting that phosphatase was not involved in the S1PR3-mediated STAT3 activation in psoriasis." (PMID 39833165, 2025). "LncRNA H19 might serve as a sponge for miR-766-3p to up-regulate S1PR3 levels and regulates the proliferation of keratinocytes and skin inflammation by AKT/mTOR pathway in psoriasis." (PMID 34992498, 2021).